MAS1L (MAS1 proto-oncogene like, G protein-coupled receptor)
Synonyms: MRG; MAS-L; dJ994E9.2
Tractability: Small molecule: it belongs to a druggable protein family. Antibody: its Gene Ontology location is reachable by antibodies, with high confidence; UniProt places it where antibodies can reach, with medium confidence; UniProt predicts a signal peptide or a membrane-spanning region; the Human Protein Atlas places it where antibodies can reach.
Target class: Family A G protein-coupled receptor; Membrane receptor
Gene: Protein-coding gene on chromosome 6 (29,486,697 to 29,487,956, reverse strand). Ensembl gene ENSG00000204687.
Subcellular location: Cell membrane
Subcellular location (Human Protein Atlas): Plasma membrane; Cytosol; Nucleoplasm
Gene Ontology:
Molecular function: G protein-coupled receptor activity
Biological process: G protein-coupled receptor signaling pathway
Cellular component: plasma membrane; membrane
Genetic constraint (gnomAD): Loss-of-function variants: 2 observed, 1.29 expected, observed/expected ratio (o/e) 1.55, 90% interval 0.47 to 1.93. That is too few expected variants to judge how well the gene tolerates losing a copy. Missense variants: 441 observed, 485.73 expected, observed/expected ratio (o/e) 0.91, 90% interval 0.84 to 0.98. Synonymous variants: 160 observed, 192.33 expected, observed/expected ratio (o/e) 0.83, 90% interval 0.73 to 0.95.
Homologues: Orthologues: guinea pig MGRH (20% identical). Paralogues in human: MRGPRX1 (29% identical), MRGPRX3 (28% identical), MRGPRX4 (28% identical), MRGPRD (27% identical), MRGPRX2 (27% identical), MAS1 (26% identical), MRGPRF (24% identical), MRGPRE (22% identical), MRGPRG (20% identical), GPR152 (15% identical).
Diseases named in the same sentence as MAS1L in open-access papers:
MAS1L is named in the same sentence as 107 diseases in open-access papers, as found by Europe PMC text mining. Sharing a sentence is not in itself a finding about the gene and the disease. The quoted sentences say what the papers report.
lung carcinoma (3 papers, 2019 to 2022). "Results showed that the signature based on MAS1L, TCP10L2, and CRHR2 is a useful tool to predict prognosis and lung cancer lymph node metastasis." (PMID 36277017, 2022).
asthma (2 papers, 2020 to 2022). "KEGG analysis showed that the terms of intestinal immune network for iga production, asthma, allograft rejection, hematopoietic cell lineage, viral myocarditis, and autoimmune thyroid disease were significantly enriched in the patients with high MAS1L level." (PMID 36277017, 2022).
MAS1L also shares sentences with these, for which no sentence is quoted: Hypertension (35 papers); COVID-19 (26); cancer (16); tumor (16); cardiovascular diseases (12); diabetes (8); Stroke (8); Anxiety (7); cardiac hypertrophy (7); endothelial dysfunction (7); Cirrhosis (6); Cognitive impairment (6); depression (6); breast carcinoma (5); Insulin resistance (5); ischemic stroke (5); portal hypertension (5); renal fibrosis (5); atherosclerosis (4); heart failure (4); liver fibrosis (4); myocardial infarction (4); Obesity (4); Alzheimer disease (3); Cerebral ischemia (3); colon cancer (3); infection (3); injury (3); periodontitis (3); Sepsis (3).
A further 75 diseases each share a sentence with MAS1L in 3 papers or fewer.